CHCHD10 (coiled-coil-helix-coiled-coil-helix domain containing 10)
Diseases named in the same sentence as CHCHD10 in open-access papers (continued):
Sharing a sentence is not in itself a finding about the gene and the disease.
motor neuron disease (9 papers, 2015 to 2025). "This study implies that CHCHD10 G66V causes motor neuron disease primarily through CHCHD10 haploinsufficiency, although the study did not examine the insolubility of these mutants." (PMID 36158221, 2022). "Increasing evidence has shown that CHCHD2 and CHCHD10 are associated with cognitive disorders and motor neuron diseases through their interactions with proteins such as OMA-1, OPA-1, TDP43, PINK, and p62." (PMID 36061599, 2022). "The CHCHD10 Gly66Val variant is commonly found in relatively mild motor neuron diseases, including late-onset spinal motor neuronopathy (spinal muscular atrophy Jokela type, SMAJ) and type 2 Charcot-Marie-Tooth disease (CMT2), both prevalent in the Finnish population." (PMID 40170896, 2025). "Whole-exome sequencing identified a missense S59L mutation in the coiled-coil-helix-coiled-coil-helix domain containing 10 (CHCHD10) gene in a large family with a late-onset phenotype including motor neuron disease, cognitive decline resembling FTD, cerebellar ataxia and myopathy." (PMID 26213621, 2015). "Coiled-coil-helix-coiled-coil-helix domain containing 10 (CHCHD10) (MIM#615903) has been identified as a causative gene in a large French family with autosomal dominant inheritance for patients with heterogeneous symptoms, including motor neuron disease, cerebellar syndrome, and cognitive decline." (PMID 36158221, 2022).
cardiomyopathy (8 papers, 2022 to 2025). A disease of the heart muscle or myocardium proper. "The primary model of cardiomyopathy used in the study was previously developed by the authors and results from a dominant disease-causing mutation (p.S59L) in the mitochondrial protein CHCHD10." (PMID 38724624, 2024). "In humans, mutations in CHCHD10 cause mitochondrial myopathy, including cardiomyopathy, in addition to Amyotrophic Lateral Sclerosis and other motor neuron disorders." (PMID 38724624, 2024). "Since HFD forces the heart to use FAO by causing insulin resistance, we sought to obtain proof of concept that HFD could exert a protective role in the cardiomyopathy associated with S55L mutant CHCHD10." (PMID 38724625, 2024). "Potentially, a HFD strategy could be employed in the pedigrees with CHCHD10 mutations that present with cardiomyopathy, whereas it is uncertain whether HFD could have beneficial effects in patients with predominantly neurological manifestations." (PMID 38724625, 2024). "The CHCHD10 G58R mutation causes autosomal dominant myopathy and cardiomyopathy." (PMID 35700042, 2022). "In another study, CHCHD10 S59L knock-in mice presented progressive motor deficits, myopathy, cardiomyopathy, and accelerated mortality." (PMID 36158221, 2022). "Using protease-inactive Oma1E324Q/E324Q knock-in mice, we show that blunting mtISR in Chchd10S55L/+ mice delays cardiomyopathy onset without rescuing CHCHD10 insolubility, cristae defects or OXPHOS impairment." (PMID 41420107, 2025). "Another study discovered that cardiomyopathy and mtISR were induced in CHCHD2/CHCHD10 double knockout mice and CHCHD10 S59L knock-in mice, but not in single knockout mice." (PMID 36158221, 2022).
spinal muscular atrophy Jokela type (6 papers, 2019 to 2025). "Another study comparing the effects of benign Jokela type spinal muscular atrophy (SMAJ)-linked CHCHD10 G66V and the more severe ALS–FTD-associated CHCHD10 S59L showed that the accumulation of phosphorylated TDP-43 is comparable among these mutants." (PMID 30791515, 2019). "Spinal muscular atrophy, Jokela type (SMAJ), also known as late-onset spinal motor neuronopathy (LOSMoN), is autosomal dominantly inherited spinal muscular atrophy caused by Finnish founder mutation c.197G>T (Gly66Val) in CHCHD10 gene." (PMID 38020590, 2023).
Cognitive impairment (4 papers, 2016 to 2024). Abnormal cognition is characterized by deficits in thinking, reasoning, or remembering. "No cognitive deficits were found in patients carrying variants in other genes, with the exception of three mutated patients in TARDPB (c.883G > A p.Gly295Ser), TBK1 (c.225G > C p.Glu75Asp), and CHCHD10 (c.100C > T p.Pro34Ser), respectively." (PMID 33770234, 2021).
Charcot-Marie-Tooth disease type 2 (3 papers, 2022 to 2025). A Charcot-Marie-Tooth disease characterized by abnormalities in the axon of the peripheral nerve cell. "Subsequent studies have also unveiled a wide range of CHCHD10-related disorders, including late-onset spinal motor neuronopathy (LOSMoN/SMAJ), axonal Charcot-Marie-Tooth disease type 2 (CMT2), Alzheimer's disease, and myopathy." (PMID 40170896, 2025).
dementia (3 papers, 2017 to 2022). Loss of intellectual abilities interfering with an individual's social and occupational functions. "Mutations of Chchd10 are associated with ALS, dementia and myopathy in humans and animal models, but how knockout of Chchd10 (Chchd10KO) affects various tissues especially skeletal muscle and adipose tissues remains unclear." (PMID 35362877, 2022).
frontotemporal lobe dementia (3 papers, 2019 to 2022). "In contrast, CHCHD10 protein levels were significantly lower in the spinal cord of patients with ALS and the frontal cortex of patients with frontotemporal lobe dementia (FTD)." (PMID 36158221, 2022).
Insulin resistance (2 papers, 2024 to 2025). Increased resistance towards insulin, that is, diminished effectiveness of insulin in reducing blood glucose levels. "We then determined if the beneficial effect of Chchd10 deficiency in combating obesity and insulin resistance (IR) is mediated through upregulating GSTA4." (PMID 39985288, 2025).
neuroblastoma (2 papers, 2017 to 2019). Neuroblastoma (NB) is the most common solid, extracranial childhood tumor. "We also analyzed images of mitochondrial networks in mouse hippocampus-derived neuroblastoma cells, transduced with wildtype, R15L, and S59L mutations of Coiled-coil-helix-coiled-coil-helix domain-containing protein 10 (CHCHD10) that were reported in Ref." (PMID 31557225, 2019).
proteinopathies (2 papers, 2022 to 2023). "Herein, we present the first in vivo evidence that the FTD/ALS-linked CHCHD10R15L and CHCHD10S59L mutations drive CHCHD10 and TDP-43 proteinopathies originating from mitochondria, which directly mirror the functional changes in long-term synaptic plasticity and motor unit physiology." (PMID 35787294, 2022). "Based on the preceding observations in post-mortem human brains, we next tested the hypothesis that FTD/ALS-linked CHCHD10 mutants, which themselves are prone to aggregation, can drive both CHCHD10 and TDP-43 proteinopathies." (PMID 35787294, 2022).
axonal neuropathy (1 paper, 2018). Any nerve disorder affecting the axon of a nerve. "AIFM1, which is required for mitochondrial targeting of Mia40, and thus indirectly of CHCHD10, has been linked to mitochondrial encephalopathy and axonal neuropathy." (PMID 29789341, 2018).
bladder cancer (1 paper, 2024). "On the TCGA bladder cancer dataset, RTCpredictor re-identified three out of six known read-throughs (ACKR2-KRBOX1, CHCHD10-VPREB3 and SLC2A11-MIF)." (PMID 38796690, 2024).
Obesity (1 paper, 2025). Accumulation of substantial excess body fat. "In long‐term energy surplus, Chchd10 deficiency protects against diet‐induced obesity and metabolic disorders, possibly by improving WAT homeostasis." (PMID 39985288, 2025). "This evidence suggested that Chchd10 deficiency promotes lipid storage in iWAT over time while alleviating chronic HFD‐induced obesity by attenuating adipocyte hypertrophy in both iWAT and eWAT." (PMID 39985288, 2025). "Taken together, these findings indicated that Chchd10 deficiency enhances energy expenditure and protects against diet‐induced obesity, possibly through alleviating diet‐induced mitochondrial dysfunction in adipocytes." (PMID 39985288, 2025). "Hence, Chchd10 deficiency attenuates diet‐induced obesity and related metabolic disorders in mice." (PMID 39985288, 2025). "As obesity progresses, the loss of p62 in adipocytes with relatively high lipid contents impairs the Chchd10‐mediated adaptive mechanism, which eventually potentiates the development of obesity and its related metabolic disorders." (PMID 39985288, 2025). "Further investigations on the safety of targeting Chchd10 for treating obesity are warranted." (PMID 39985288, 2025). "Through activating the TDP43/Raptor/p62/Keap1/NRF2 axis, the reduction of Chchd10 in response to energy surplus awakens the adaptive response, which potentiates adipogenesis and GSTA4‐mediated 4‐HNE clearance to combat obesity." (PMID 39985288, 2025). "On the other hand, sustained Chchd10 reduction protects visceral AT from 4‐HNE‐induced adipocyte dysfunction, attenuating the development of obesity and related metabolic disorders." (PMID 39985288, 2025). "Collectively, the present findings identify p62 as a key modulator of the Chchd10‐reduction mediated adaptive response and its reduction in hypertrophic adipocytes may lead to the conversion of flexible adipose tissue to rigid dysfunctional adipose tissue during the development of obesity." (PMID 39985288, 2025). "On the other hand, Chchd10 reduction‐mediated upregulation of GSTA4 improves mitochondrial functions to prevent adipocyte hypertrophy and combat obesity." (PMID 39985288, 2025).
primary progressive aphasia (1 paper, 2025). Primary progressive aphasia (PPA) is a neurodegenerative disorder, characterized by a primary dissolution of language, with relative sparing of other mental faculties for at least the first 2 years of illness. "One study reported the co-occurrence of CHCHD10 and C9orf72 variants in an ALS-FTD patient, and another reported a person carrying both TBK1 and SQSTM1 variants, who was diagnosed with non-fluent variant primary progressive aphasia (nfv-PPA)." (PMID 40170896, 2025).
neurodegenerative disease (23 papers, 2017 to 2026). A disorder of the central nervous system characterized by gradual and progressive loss of neural tissue and neurologic function. "In line with the association of CHCHD10 with neurodegenerative disease such as ALS, a mouse model expressing a patient mutation in CHCHD10 displayed progressive NMJ degeneration, including motor neuron loss." (PMID 37239850, 2023). "CHCHD10 is implicated in neurodegenerative diseases as inducing aggregation of TDP-43, a pathological feature of several neurodegenerative diseases Moreover, amyloid-like myo-granules were formed by TDP-43 and RNA in regenerating muscle." (PMID 35362877, 2022). "CHCHD2 and CHCHD10 are homologous mitochondrial proteins and their mutations are identified with neurodegenerative disease." (PMID 35173147, 2022). "While CHCHD2 and CHCHD10 share significant similarities in sequence, secondary structure, expression pattern, and function, mutations in CHCHD2 and CHCHD10 are associated with distinctly different neurodegenerative diseases." (PMID 33967741, 2021). "Further, we discuss the necessity of continued investigation into the divergent functions of CHCHD2 and CHCHD10 to determine how mutations in these similar mitochondrial proteins contribute to different neurodegenerative diseases." (PMID 33967741, 2021). "Although CHCHD2- and CHCHD10-linked neurodegenerative diseases are dominantly inherited, the findings of their mutations leading to premature protein truncation suggest mitochondrial phenotypes arise from haploinsufficiency." (PMID 30791515, 2019). "Subsequent studies have demonstrated that CHCHD2 and CHCHD10 are associated with a variety of dominantly inherited neurodegenerative diseases as well as sporadic neurodegenerative diseases." (PMID 30791515, 2019). "We discuss mutations in both MNRR1 and CHCHD10 found in a number of chronic, mostly neurodegenerative, diseases." (PMID 28685009, 2017). "Mitochondrial dysfunction has been linked to other neurodegenerative diseases and may explain the broad clinical symptoms associated with CHCHD10 mutations." (PMID 29789341, 2018). "In recent years, mutations at two mitochondrial homologous proteins CHCHD2 and CHCHD10 have been identified as a wild spectrum of neurodegeneration disease." (PMID 35173147, 2022). "This review synthesizes evidence related to the functions of CHCHD2 and CHCHD10 and their molecular mechanisms in the progression of neurodegenerative diseases, providing implications for novel strategies in brain injury." (PMID 36061599, 2022). "In this review, we summarize the present knowledge about the physiological and pathological roles of twin proteins, CHCHD2 and CHCHD10, in neurodegenerative diseases." (PMID 30791515, 2019). "In this review, we will focus on two of these proteins that have very recently been associated with neurodegenerative diseases, MNRR1/CHCHD2 and CHCHD10." (PMID 28685009, 2017). "CHCHD10 and CHCHD2 are mitochondrial proteins that reside in the intermembrane space and regulate electron flow through the electron transport chain during oxidative phosphorylation, and have been linked to multiple neurodegenerative diseases." (PMID 41496579, 2026). "Our findings from FTLD-TDP and AD cases showing robust colocalization phospho-TDP-43 pathology with CHCHD10 inclusions (~ 75–84%) and tight correlation between insoluble CHCHD10 with insoluble TDP-43 indeed indicates a pathological link between them in human neurodegenerative diseases." (PMID 35787294, 2022). "Thus, although neurodegenerative diseases may be generally associated with myopathy, the basis of CHCHD10-mediated clinical pleiotropy is not understood." (PMID 33772006, 2021). "Identification of mutant CHCHD10 in ALS-FTD and related diseases and its predominant localization in mitochondria provide an opportunity to investigate the mitochondrial origin of neurodegenerative diseases." (PMID 33772006, 2021).
neurodegenerative disease (continued). "Therefore, investigating the protective role of CHCHD10 in ALS-FTD and other degenerative diseases with mitochondrial defects is important." (PMID 33772006, 2021).
myopathy (11 papers, 2015 to 2025). A disease of the muscle in which the muscle fibers do not function properly. "Together, this argues against LoF and in favor of toxic gain-of-function as the mechanism of disease pathogenesis, similar to the myopathy-causing variants in CHCHD10 (p.G58R and p.S59L)." (PMID 41040684, 2025). "Here, we characterize a family with myopathy caused by a dominant p.G58R mutation in the mitochondrial protein CHCHD10." (PMID 35700042, 2022). "The data also suggest that human CHCHD10 mutations cause myopathy through a gain-of-function mechanism." (PMID 35362877, 2022).
mitochondrial disease (4 papers, 2020 to 2025). "Mutations in CHCHD10, a mitochondrial intermembrane space (IMS) protein implicated in proteostasis and cristae maintenance, cause mitochondrial disease." (PMID 41420107, 2025).
neurological disease (4 papers, 2020 to 2022). "Transcriptome analysis identified new responders to mitochondrial protein import toxicity, such as the neurological disease-linked intermembrane space protein CHCHD10." (PMID 36198903, 2022). "Mutations in CHCHD2 and CHCHD10 can lead to neurological diseases, while CHCHD2 and CHCHD10 are degraded by proteases under stress conditions." (PMID 35173147, 2022). "Many genes play an important role, with TARDBP, SQSTM1, VCP, FUS, TBK1, CHCHD10, and most importantly, C9orf72 being critical genetic players in these neurological disorders." (PMID 33805659, 2021). "TARDBP, SQSTM1, VCP, FUS, TBK1, CHCHD10, and most importantly C9orf72, are the critical genetic players in these neurological disorders." (PMID 32116499, 2020).
autosomal dominant disease (1 paper, 2024). Autosomal dominant form of disease. "Coiled-helix-coiled-helix domain containing 10 (CHCHD10) mutations cause autosomal dominant diseases, including fatal mitochondrial cardiomyopathy." (PMID 38724625, 2024).
CHCHD10 also shares sentences with these, for which no sentence is quoted: cerebellar ataxia (5 papers); cognitive decline (3); Parkinson's (3); Alzheimer disease (2); amyotrophic lateral sclerosis 2 (2); breast carcinoma (2); Lewy body dementia (2); spinal muscular atrophy (2); amyloidosis (1); Brugada syndrome (1); cancer (1); central nervous system disorder (1); Charcot-Marie-Tooth disease (1); cognitive disorder (1); deficiencies (1); Huntington disease (1); liposarcoma (1); liver (1); metabolic disorders (1); Mitochondrial encephalopathy (1); neuropathy (1); Noonan syndrome (1); Onset (1); sarcopenia (1); schizophrenia (1); sporadic amyotrophic lateral sclerosis (1).